UBE2S (ubiquitin conjugating enzyme E2 S)
Diseases named in the same sentence as UBE2S in open-access papers (continued):
Sharing a sentence is not in itself a finding about the gene and the disease.
ovarian carcinoma (continued). "Finally, considering that the PI3K/AKT/mTOR signaling pathway is commonly activated in ovarian cancer and plays an important role in the regulation of cell cycle and apoptosis, we attempted to explore the effect of UBE2S knockdown on the PI3K/AKT/mTOR signaling pathway." (PMID 35658829, 2022). "However, whether UBE2S affects some cell signaling pathways in ovarian cancer still needs to be further explored in detail." (PMID 35658829, 2022). "Thus, the enzymatic activity of UBE2S is required to promote ovarian cancer proliferation." (PMID 34535173, 2021). "Suppression of UBE2S expression enhances apoptosis and impedes cell cycle progression via restraining PI3K/AKT/mTOR signaling, thereby restraining ovarian cancer prognosis, migration, and proliferation." (PMID 38312603, 2024). "To exam the biological significance of UBE2S in ovarian cancer, we stably transfected A2780 and SKOV3 cells with PLKO.1 (Ctr), UBE2S shRNA1 (sh-1), UBE2S shRNA2 (sh-2), PCMV (Ctr), and PCMV-UBE2S (UBE2S)." (PMID 34535173, 2021). "Thus, targeted inhibition of UBE2S might overcome Olaparib resistance in ovarian cancer." (PMID 34535173, 2021). "Thus, we speculated that UBE2S activates the Wnt/β-catenin signaling pathway in ovarian cancer." (PMID 34535173, 2021). "All these results showed that the expression of UBE2S was extensively upregulated in HGSOC, indicating a possible role of UBE2S in ovarian cancer." (PMID 34535173, 2021). "Previous research has shown that DNA methylation can exert a negative modulation on UBE2S expression in ovarian cancer, rectal adenocarcinoma, testicular germ cell tumor (TGCT), and so on." (PMID 41427004, 2025). "First, the experimental identification of the comprehensive molecular mechanism of action of UBE2S in ovarian cancer was not comprehensive." (PMID 35658829, 2022). "Besides, C95S mutant of UBE2S failed to confer the ovarian cancer cells to proliferation, indicating that the function of UBE2S depended on its catalytic activity." (PMID 34535173, 2021). "Furthermore, UBE2S might accelerate the cell cycle and inhibit apoptosis by promoting PI3K/AKT/mTOR and ultimately drive the malignant biological behavior of OV cells, which may provide new ideas for prognostic evaluation and molecular therapy of ovarian cancer." (PMID 35658829, 2022).
lung carcinoma (10 papers, 2020 to 2025). "Analysis of breast or lung tumors using KM-plotter showed that Ube2S high expression is strongly associated with poor survival in breast and lung cancer." (PMID 41359628, 2025). "The clinicopathological analysis showed that overexpression of Ube2S was significantly associated with lung cancer progression." (PMID 32038111, 2020). "UBE2S expression in lung cancer resulted in binding with IκBα to activate NF-κB signaling and cancer cell metastasis." (PMID 37920509, 2023). "Overexpression of UBE2S has also been observed in lung cancer cell lines where UBE2S silencing reduces colony formation and increased apoptosis." (PMID 33805973, 2021). "Upregulation of UBE2S has been observed in human lung cancer tissues and is correlated with poor prognosis." (PMID 34199813, 2021). "In this study, we examined the expression of Ube2S in lung cancer and normal lung tissues, and investigated its impact on cancer cell biology, and related molecules and pathways." (PMID 32038111, 2020). "An immunostaining study showed that the positive rate of Ube2s expression in lung cancer tissues was higher than that in normal lung tissues (p < 0.05)." (PMID 32038111, 2020). "UBE2S contributes to lung cancer development by regulating canonical Wnt signaling." (PMID 37920509, 2023). "In addition, UBE2S also promotes the development of lung cancer through the canonical Wnt signaling pathway." (PMID 38115063, 2023). "This indicates that Ube2S may promote lung cancer progression by regulating canonical Wnt signaling." (PMID 32038111, 2020). "In the current study, we investigated whether Ube2S regulated lung cancer cell proliferation through the canonical Wnt pathway." (PMID 32038111, 2020). "However, the association study did not reveal the cause or consequence of UBE2C/UBE2S overexpression in lung cancer development." (PMID 36548081, 2023). "We first performed an association study using TCGA database containing more than 400 lung cancer cases, and found that overexpression of either UBE2C or UBE2S is correlated with the survival of LUAD patients." (PMID 36548081, 2023). "Western blotting showed that Ube2S was expressed in bronchial epithelial HBE cells and lung cancer cell lines including A549 and NCI-H1299." (PMID 32038111, 2020). "To address this, we first used an in vitro cell culture system and confirmed that UBE2C, but not UBE2S, is essential for the growth and survival of lung cancer cells harboring a mutant Kras." (PMID 36548081, 2023). "Knockdown of UBE2C, but not UBE2S, inhibits growth of lung cancer cells." (PMID 36548081, 2023).
colorectal cancer (9 papers, 2016 to 2026). A primary or metastatic malignant neoplasm that affects the colon or rectum. "Among E3 ligases used in proteolysis-targeting chimeras (PROTACs), VHL was upregulated together with its E2-conjugating enzyme UBE2S in colorectal cancers." (PMID 41898804, 2026). "Research has shown that UBE2S is a crucial factor to determine the malignant characteristics in human colorectal cancer." (PMID 38312603, 2024). "UBE2S mediates tumor progression through regulating Wnt/β-catenin signaling in colorectal cancer and non-small cell lung cancer." (PMID 34535173, 2021). "Specifically, UBE2S could stabilize β-catenin with the help of K11 polyubiquitin chains, thereby promoting mesodermal specification and the development of colorectal cancer." (PMID 38312603, 2024). "Moreover, we demonstrated that UBE2S plays a critical role in determining the malignancy properties of human colorectal cancer (CRC) cells in vitro and in vivo." (PMID 29674637, 2018). "Meanwhile, it enhanced the malignancy properties of colorectal cancer (CRC) both in vitro and in vivo, which can be markedly reduced upon UBE2S deletion alone." (PMID 29674637, 2018).
endometrial cancer (9 papers, 2020 to 2024). Primary or metastatic malignant neoplasm involving the endometrium (mucous membrane that lines the endometrial cavity). "Ultimately, the transactivation of endometrial cancer progression via SOX6/β-linked protein signaling is facilitated by UBE2S." (PMID 38312603, 2024). "The upregulation of UBE2S in endometrial cancer has been demonstrated to be significantly associated with a poor prognosis." (PMID 38312603, 2024). "In this study, UBE2S expression levels in endometrial cancer tissues were found to be higher than those in normal tissues, and UBE2S was found to be closely associated with endometrial cancer prognosis." (PMID 36611207, 2023). "Therefore, UBE2S is a potential diagnostic and therapeutic target for endometrial cancer." (PMID 36611207, 2023). "In endometrial cancer, UBE2S promotes the proliferation and migration of endometrial cancer cells through SOX6/β-Catenin signaling." (PMID 36611207, 2023). "In summary, downregulating UBE2S expression or upregulating ASB2 expression in tumors is a potential treatment strategy for endometrial cancer." (PMID 36611207, 2023). "Ube2S was also found to be overexpressed in some cancers, including breast, hepatocellular, and endometrial cancer, and to be related to cancer progression 4-8." (PMID 32038111, 2020). "Furthermore, UBE2S is highly expressed in a variety of malignancies, including brain, cervical, colon, liver, ovarian, lung, breast, and endometrial cancers." (PMID 38312603, 2024). "In addition, among the genes closely associated with PPP1R14B expression, UBE2S, JPT1, and PTTG1 were associated with abnormal expression of endometrial cancer desiccations, proliferation, migration, methylation, and prediction of response to metformin therapy." (PMID 36824011, 2023). "In addition, other studies have shown that UBE2S could inhibit the tumor progression of endometrial cancer through the SOX6/β-Catenin signaling pathway." (PMID 35658829, 2022). "The ectopic expression of UBE2S promoted cell proliferation and migration via regulating SOX6/β-Catenin in endometrial cancer (EMC)." (PMID 34535173, 2021). "The β-catenin blockade inhibits UBE2S-induced cancer cell expansion, suggesting that components of the UBE2S-SOX6/β-catenin axis are possible therapeutic targets of endometrial cancer." (PMID 33805973, 2021). "Ubiquitin-conjugating enzyme E2 S (UBE2S) overexpression enhances migration and growth of endometrial cancer cells, while silencing it can reverse these effects." (PMID 33805973, 2021).
cervical cancer (7 papers, 2020 to 2025). A primary or metastatic malignant neoplasm involving the cervix. "UBE2S expression level in cervical cancer was demonstrated to have a positive association with the AJCC stage." (PMID 41427004, 2025). "Prior research has indicated that the inhibition of UBE2S enhances the susceptibility of cervical cancer HeLa cells to etoposide and adriamycin, as well as heightens the chemosensitivity to topotecan." (PMID 38312603, 2024). "For example, quercetin inhibits cervical cancer cell invasion by reducing UBE2S expression in cervical cancer." (PMID 35369029, 2022). "Previous studies report that UBE2S knockdown increases sensitivity of cervical cancer HeLa cells to etoposide and doxorubicin." (PMID 34123793, 2021). "UBE2S may have a significant influence on cervical cancer invasion and metastasis by the pathway of pVHL‐HIF." (PMID 41427004, 2025). "Furthermore, the impact of UBE2S on the ability of cell tumorigenesis, invasion and proliferation for the cervical cancer cell lines was observed to be mediated by the promotion of HIF-1α expression." (PMID 38312603, 2024). "Our findings suggest that the downregulation of UBE2S expression by lignocaine and quercetin may inhibit epithelial-mesenchymal transition (EMT) and impede cervical cancer metastasis, thereby highlighting UBE2S as a promising therapeutic target for cervical cancer." (PMID 38312603, 2024). "Lately, Ube2s was found to have a positive correlation with HIF-1α signaling in renal and cervical cancer cells." (PMID 32250966, 2020). "Knocking down UBE2S could inhibit EMT cell signaling and inhibits invasion of cervical cancer." (PMID 34384030, 2021).
lung adenocarcinoma (6 papers, 2022 to 2025). A carcinoma that arises from the lung and is characterized by the presence of malignant glandular epithelial cells. "The activation of NF-κB signaling through binding to IκBα by UBE2S has been found to promote metastasis in lung adenocarcinoma cells." (PMID 38312603, 2024). "Ultimately, UBE2S facilitates the metastasis of lung adenocarcinoma cells by means of activating NF-κB signaling through its binding to IκBκ." (PMID 38312603, 2024). "UBE2S activated the NF-κB signaling pathway in lung adenocarcinoma cells and triggered the expression of downstream EMT markers." (PMID 38312603, 2024). "High expression of UBE2S activates the NF-κB pathway and promotes the metastasis of lung adenocarcinoma." (PMID 36712848, 2022). "Additionally, analysis of publicly available datasets revealed a significant upregulation of UBE2S in lung adenocarcinoma (LUAD) and lung squamous cell carcinoma (LUSC) tissues." (PMID 41254082, 2025). "It is hypothesized that elevated expression of UBE2S in lung adenocarcinoma may result in heightened binding to IκBα, thereby activating NF-κB signaling and promoting metastasis of adenocarcinoma cells." (PMID 38312603, 2024). "Furthermore, it was proposed that the administration of Ly294002 resulted in a reduction of UBE2S protein levels and an increase in IκBα protein levels within lung adenocarcinoma cells." (PMID 38312603, 2024). "Thus, UBE2S presents itself as a promising therapeutic target for lung adenocarcinoma." (PMID 38312603, 2024). "Elevated expression of UBE2S is linked to a negative prognosis in individuals with lung adenocarcinoma, and UBE2S facilitates cellular proliferation, colony formation, and impedes apoptosis in human lung adenocarcinoma cells." (PMID 38312603, 2024).
glioblastoma (5 papers, 2020 to 2024). The most malignant astrocytic tumor (WHO grade IV). "Furthermore, we identified five UBE2S ubiquitination sites and found that UBE2S was associated with Akt phosphorylation in malignant glioblastoma." (PMID 34123793, 2021). "Downregulation of UBE2S expression in Glioblastoma (GBM) suppressed NHEJ-mediated DSBR, and made GBM cells more sensitive to radiotherapy." (PMID 33810518, 2021). "To summarize, UBE2S represents a newly identified Akt1 substrate that could bind to Ku70 to govern chemoresistance and DNA repair in glioblastoma multiforme." (PMID 38312603, 2024). "Moreover, the inhibition of expression level of UBE2S restrained NHEJ-mediated DSB repair and increased the susceptibility of glioblastoma cells to chemotherapy." (PMID 38312603, 2024). "In addition, the high expression of UBE2S in glioblastoma multiforme induces resistance to chemotherapy." (PMID 37563971, 2023).
melanoma (5 papers, 2012 to 2023). A malignant, usually aggressive tumor composed of atypical, neoplastic melanocytes. "Treatment of melanoma cells with a short hairpin RNA targeting UBE2S led to cell cycle arrest in the G1/S phase and inhibition of cancer cell growth." (PMID 33810518, 2021). "Depletion of UBE2S using short hairpin RNA in melanoma cells resulted in an inhibition of proliferation, a cell cycle arrest, and an increase in apoptosis." (PMID 33800394, 2021). "The expression levels in metastatic melanoma tumours of two of these genes (UBE2S and TMCO1) appear to be significantly associated with the time to relapse in melanoma patients." (PMID 22536322, 2012). "The ubiquitin-conjugating enzyme E2S (UBE2S) could also play a role in melanoma and be an appealing target." (PMID 33800394, 2021). "UBE2S was found to be highly expressed in most tumor tissues, while MIA was mainly concentrated in tumor tissues of melanoma (SKCM)." (PMID 37479876, 2023).
non-small cell lung carcinoma (5 papers, 2020 to 2022). A group of at least three distinct histological types of lung cancer, including non-small cell squamous cell carcinoma, adenocarcinoma, and large cell carcinoma. "In the current study, we examined the expression of Ube2S in non-small cell lung cancer and its clinicopathological significance." (PMID 32038111, 2020). "However, the functions and related molecular network of Ube2S in non-small cell lung cancer are not fully understood." (PMID 32038111, 2020). "However, the function, and molecules and pathways regulated by Ube2S in non-small cell lung cancer (NSCLC), are not fully understood." (PMID 32038111, 2020).
prostate carcinoma (5 papers, 2020 to 2024). A carcinoma that arises from epithelial cells of the prostate gland. "Furthermore, UBE2S has been observed to stabilize β-catenin through K11-linked ubiquitination, thereby enhancing the invasion and migration of cancer cells in the context of prostate cancer bone metastases." (PMID 38312603, 2024). "Ultimately, UBE2S plays a crucial role in the promotion of bone metastasis in prostate cancer by facilitating the degradation of p11 and stabilizing β-catenin via K16-linked ubiquitination." (PMID 38312603, 2024).
bladder cancer (3 papers, 2022 to 2025). "In addition, studies have shown that knockdown of UBE2S promotes apoptosis, inhibits cell proliferation, and inhibits the mTOR signaling pathway in vitro and in vivo, thereby ultimately inhibiting the tumor progression of bladder cancer." (PMID 35658829, 2022).
lymph node metastasis (3 papers, 2020 to 2025). "Upregulated Ube2S expression in cancer tissues significantly correlated with clinical progression (TNM III versus I + II), lymph node metastasis, and shorter survival time of the patients (p < 0.05)." (PMID 32038111, 2020). "From the results, no statistical significance was detected between the UBE2S expression and lymph node metastasis, differentiation degree, and AJCC." (PMID 41427004, 2025).
pancreatic cancer (3 papers, 2020 to 2024). "The study revealed that in pancreatic cancer cells, the expression of the UBE2S gene facilitated the process of epithelial-mesenchymal transition (EMT) by means of the ubiquitin proteasome system and the interaction between UBE2S and VHL." (PMID 38312603, 2024). "This indicates UBE2S takes part in promoting endodermal metastasis and metastasis in pancreatic cancer cells in vitro and in vivo by inhibiting promoter activity in the VHL/HIF-1α/STAT3 pathway." (PMID 38312603, 2024). "Moreover, UBE2S could form an important ubiquitin ligase APC/C with ANAPC2/4, whereas CDC20 could regulate APC/C, activating other significant factors in EMT progression, such as E-cadherin by ubiquitin, to affect the invasion and metastasis of pancreatic cancer." (PMID 37682144, 2023).
breast tumor (2 papers, 2019 to 2023). "Following the current study by TCSBN correlation analysis of SERTAD1 in cancer and normal tissue, SERTAD1 significantly correlated with JOSD2 (Corr = 6.15) and UBE2S (Corr = 0.588) in breast tumor and normal tissue respectively." (PMID 30857225, 2019). "In conclusion, UBE2S and UBE2C both inhibited Numb expression and promoted breast tumor malignancy." (PMID 36860312, 2023).
gastric cancer (2 papers, 2021 to 2024). A primary or metastatic malignant neoplasm involving the stomach. "Both UbcH10 and Ube2S are overexpressed in human cancers and elevated expression of Ube2K is associated with a poor prognosis in pancreatic and gastric cancers." (PMID 34586382, 2021). "The present study has revealed that UBE2S was abnormally highly expressed in both gastric cancer tissues and cells." (PMID 38312603, 2024).
malignant glioma (2 papers, 2021 to 2024). A grade III or grade IV glioma arising from the central nervous system. "The findings indicate that the abnormally high expression of UBE2S is associated with more malignant gliomas and PTEN mutations, while a negative correlation was observed between UBE2S expression and 1p19q deletion and IDH1 mutations." (PMID 38312603, 2024).
myocardial ischemia (2 papers, 2020 to 2024). A disorder of cardiac function caused by insufficient blood flow to the muscle tissue of the heart. "In recent years, UBE2S has emerged as a significant epigenetic modification in various diseases, including myocardial ischemia, viral hepatitis, and notably, cancer." (PMID 38312603, 2024).
pancreatic ductal adenocarcinoma (2 papers, 2021 to 2025). An infiltrating adenocarcinoma that arises from the epithelial cells of the pancreas. "UBE2S was demonstrated to promote the epithelial-mesenchymal transition (EMT) through the VHL/HIF-1α/STAT3 signaling pathway in pancreatic ductal adenocarcinoma." (PMID 34535173, 2021). "UBE2S had the ability to raise the EMT in pancreatic ductal adenocarcinoma." (PMID 41427004, 2025).
brain glioma (1 paper, 2023). A malignant glioma that involves the brain. "In addition, high expression of UBE2S indicates a more unfavourable prognosis in oesophageal squamous cell carcinoma and brain glioma." (PMID 37563971, 2023).
carcinoma of the oral squamous cell (1 paper, 2025). "In carcinoma of the oral squamous cell, UBE2S expression was positively connected with the primary tumor size." (PMID 41427004, 2025).